BDNF (brain derived neurotrophic factor)
Diseases named in the same sentence as BDNF in open-access papers (continued):
Sharing a sentence is not in itself a finding about the gene and the disease.
ganglion (1 paper, 2025). "Their pathogenesis involves glutamate excitotoxicity, oxidative stress, reduced optic nerve perfusion, microglial activation, and decreased brain-derived neurotrophic factor (BDNF), leading to retinal ganglion cell damage." (PMID 40724899, 2025).
Genetic obesity (1 paper, 2023). "In general, hypothalamic TrkB.FL overexpression resembles the metabolic outcomes induced by hypothalamic BDNF overexpression in C57BL/6 mice of normal weight as well as genetic obesity and DIO models on C57BL/6 background." (PMID 36893171, 2023).
Hallux valgus (1 paper, 2022). Lateral deviation of the great toe (i.e., in the direction of the little toe). "Besides, in the postoperative recovery of the hallux valgus surgery, the liquor BDNF after two a-tDCS sessions was associated with lower pain scores and disability due to pain 7 days after surgery." (PMID 36504629, 2022).
helminth infection (1 paper, 2013). "Correale and colleagues showed increased production of BDNF and nerve growth factor in stimulated B cells from MS patients with a helminth infection compared to uninfected patients and controls." (PMID 24351232, 2013).
hip fracture (1 paper, 2015). Traumatic or pathological injury to the hip in which the continuity of either the femoral head, femoral neck, intertrochanteric or subtrochanteric regions is broken. "Results indicate hip fracture participants with two BDNF Met alleles have higher depressive symptoms than Val/Val carriers in the first weeks post-fracture." (PMID 25781924, 2015). "Among 429 participants with hip fracture, BDNF Met/Met carriers developed significantly more depressive symptoms than Val/Val carriers during a four-week period after the fracture (p=.012)." (PMID 25781924, 2015).
HIV dementia (1 paper, 2023). "In accordance, less BDNF was found in the brains of HIV-infected persons with HIV dementia than those without, possibly due to an impaired ratio of proBDNF to mature BDNF." (PMID 36790601, 2023).
hyperaldosteronism (1 paper, 2019). Overproduction of aldosterone by the adrenal glands, which may lead to hypokalemia and/or hypernatremia. "Though single, acute stimulation of mineralocorticoid receptors affected BDNF expression in several brain regions, no changes in BDNF expression were induced in the present animal model of hyperaldosteronism." (PMID 31044578, 2019).
Hyperhidrosis (1 paper, 2025). Abnormal excessive perspiration (sweating) despite the lack of appropriate stimuli like hot and humid weather. "Western blot analysis revealed that treatment with Polydatin (50 mg/kg/day for 1 week) significantly reduced the protein expression of BDNF and NRG-1 in the sympathetic ganglia compared to untreated hyperhidrosis mice (p = 0.009 and p = 0.035, respectively)." (PMID 40880648, 2025). "In conclusion, this study demonstrates that Polydatin alleviates hyperhidrosis symptoms in a mouse model by downregulating AQP5 and NKCC1 expression in sweat glands and reducing neurogenic factors such as BDNF and NRG-1 in sympathetic ganglia." (PMID 40880648, 2025). "Polydatin significantly reduced the expression of both BDNF and NRG-1 in sympathetic ganglia, suggesting that it may attenuate hyperhidrosis by dampening sympathetic overactivation." (PMID 40880648, 2025).
hypocortisolemia (1 paper, 2019). "Individuals with hypocortisolemia, both patients and controls, presented lower serum BDNF levels when compared to volunteers with eucortisolemia (patients and controls)." (PMID 31231276, 2019). "However, at baseline, serum cortisol was a predictor of serum BDNF levels, where lower levels of serum BDNF were detected in a subgroup of subjects with hypocortisolemia." (PMID 31231276, 2019).
Hypokalemia (1 paper, 2024). An abnormally decreased potassium concentration in the blood. "BDNF can also increase neuronal growth, maturation, and differentiation of nerve cells and can protect cerebellum granular cells from apoptosis due to loss of glucose or hypokalemia." (PMID 39810851, 2024).
hypospadias (1 paper, 2022). Hypospadias is the displacement of the urethral meatus on the ventrum of the penis. "Additionally, investigation of cases with hypospadias and variants in genes enriched in multiple tissues (e.g., ADAMTSL1, BDNF) may potentially lead to the identification of new syndromes, or the expansion of phenotypes for existing syndromes." (PMID 35457073, 2022).
ideomotor apraxia (1 paper, 2025). A form of apraxia characterized by an acquired inability to carry out a complex motor activity despite the ability to mentally formulate the action. "IVR has been shown to effectively improve symptoms of ideomotor apraxia, induce positive changes in inflammation levels, oxidative stress, and BDNF serum biomarkers, and enhance functional evaluation scores in individuals with chronic stroke." (PMID 40431872, 2025).
impulse control disorder (1 paper, 2024). A category of behaviors that can be loosely defined as the failure to resist an impulsive act or behavior that may be harmful to self or others. "BDNF was also linked to impulse-control disorders; functional polymorphism of BDNF rs6265 (Val66Met) was indicated as significant for attentional impulsivity in methamphetamine abusers." (PMID 39452910, 2024).
insulin-resistant diabetes (1 paper, 2022). "Furthermore, formalized paraphrase in db/db mice, a model of insulin-resistant diabetes, CR, wheel running, or a combination of both increased the hippocampal BDNF level, which was accompanied by increases in dendritic spine density on the secondary and tertiary dendrites of dentate granule neurons." (PMID 36235760, 2022).
insulinoma (1 paper, 2021). "It was observed that DOX significantly inhibited BDNF production with a dose-dependent manner, while BDNF prevented apoptosis and restored the antioxidant levels in rat insulinoma cells." (PMID 33477900, 2021).
iron overload (1 paper, 2024). "To confirm whether the elevated iron content in the hippocampus induced the release of TNF-α and in turn downregulated the expression of BDNF, we established a hippocampal iron overload mouse model by injecting FAC into the hippocampus of 6-week-old C57BL/6 mice." (PMID 38195497, 2024).
ischemia reperfusion injury (1 paper, 2025). Adverse functional, metabolic, or structural changes in ischemic tissues resulting from the restoration of blood flow to the tissue (reperfusion), including swelling; hemorrhage; necrosis; and damage from free radicals. "This SCFA-mediated BDNF upregulation activates the PI3K/AKT signaling cascade, which phosphorylates and inactivates pro-apoptotic proteins BDNF and increases antioxidant expression, as shown in a model of ischemia reperfusion injury." (PMID 41009038, 2025).
Joint effusion (1 paper, 2023). "Joint effusion is associated with growth factors (BDNF, FGF, IGFBP), stromelysin, and MMP-inhibitor, while joint movement pain and degradation are associated with TIMP-1, ADAMT-4, and ADAMT-5 biomarkers." (PMID 37241010, 2023).
juvenile arthritis (1 paper, 2019). "Therefore, it is speculated that LAC treatment, via normalizing glutamate overflow and BDNF expression, may have fast positive effects on the neuropsychiatric symptoms in juvenile arthritis patients." (PMID 30625990, 2019).
keloid (1 paper, 2025). An irregularly shaped, elevated mark on the skin caused by deposits of excessive amounts of collagen during wound healing. "Ultimately, 7 hub genes—EDN1, NTF3, VCAM1, ADRB2, BDNF, F3 and FLT1—were identified, all of which had interaction scores above 0.70, indicating their potential roles in keloid formation and progression." (PMID 40051702, 2025). "The heatmap illustrates the differential expression of these 13 OSRDEGs between keloid and normal skin tissues, where F3, FOXL2, EDN1, and NTF3 show higher expression in keloid tissues, while BDNF, FLT1, VCAM1 and ADRB2 are more highly expressed in normal skin." (PMID 40051702, 2025).
Kennedy disease (1 paper, 2025). Kennedy's disease, also known as bulbospinal muscular atrophy (BSMA), is a rare X-linked recessive motor neuron disease characterized by proximal and bulbar muscle wasting. "In support of this finding, BDNF has been shown to recover contractile strength in fast‐twitch muscle fibers of mouse models of Kennedy's disease, suggesting a potential influence of BDNF on muscle contractile properties." (PMID 39853792, 2025).
Lafora disease (1 paper, 2014). Lafora disease (LD) is a rare, inherited, severe, progressive myoclonic epilepsy characterized by myoclonus and/or generalized seizures, visual hallucinations (partial occipital seizures), and progressive neurological decline. "Altered NGF and BDNF metabolism could be induced or exasperated by neurodegeneration in the brain of patients with Lafora disease." (PMID 24472629, 2014). "The altered metabolism of NGF and BDNF could be induced or aggravated by the neurodegeneration in the brain patients with Lafora disease." (PMID 24472629, 2014). "However, our results suggest that impairment of p75NTR signalling and altered neurotrophins levels (NGF and BDNF) could be involved in the neurodegenerative processes of Lafora disease in the cerebral cortex." (PMID 24472629, 2014).
large cell neuroendocrine carcinoma (1 paper, 2016). A usually aggressive carcinoma composed of large malignant cells which display neuroendocrine characteristics. "Although BDNF/TrkB signaling is involved in tumorigenicity and malignant progression to invasiveness in large cell neuroendocrine carcinoma (LCNEC) and may be a potential target in LCNEC26, 27, how this signaling is activated is not well understood." (PMID 27456333, 2016).
leprosy (1 paper, 2020). Leprosy is a chronic infectious disease affecting primarily the skin and peripheral nervous system. "In our study, the decrease of BDNF in nude mice infected by vML for eight months, suggests that the availability of these growth factors become deficient in the long turn, failing to sustain the plasticity of peripheral nerves affected by leprosy." (PMID 32696914, 2020). "One study demonstrated that BDNF levels tend to be lower in leprosy patients than in healthy individuals, which might reflect how ML-infection triggers the loss of neurotrophic stimulus by BDNF downregulation." (PMID 32696914, 2020). "Multiple neurotrophin-related signaling pathways are involved in nerve damage and repair and the role of neurotrophins in leprosy have already been approached, mainly regarding two neurotrophins, NGF and BDNF." (PMID 32696914, 2020). "Studies evaluating BDNF, and NT3/4 levels during leprosy are remarkably scarce and not updated, but their role in other neuropathy have been explored and allow the speculation on their impact on leprosy." (PMID 32696914, 2020).
limb ischemia (1 paper, 2024). A ischemia that involves the limb. "Both BDNF and NT-3 proteins display not only their trophic activity but also act as angiogenic factors as found in a mouse model of limb ischemia." (PMID 39334869, 2024).
lumbar spinal stenosis (1 paper, 2024). A spinal stenosis that involves the lumbar region of vertebral column. "Q Li, Y Liu, Z Chu, J Chen, F Dai, X Zhu, A Hu and C Yun reported an increase in BDNF expression in DRG of rat models of lumbar spinal stenosis that was inversely associated with pain severity and walking distance, consistent with the current results." (PMID 38671372, 2024).
lymphangioleiomyomatosis (1 paper, 2020). A multifocal neoplasm with perivascular epithelioid cell differentiation affecting almost exclusively females of child-bearing age. "Metabolomic profiling of polyamine metabolism (upregulation of 5′-methylthioadenosine) and brain derived neurotrophic factor were suggested as candidate markers associated with autophagy in lymphangioleiomyomatosis." (PMID 32410999, 2020).
male infertility (1 paper, 2022). The inability of the male to effect fertilization of an ovum after a specified period of unprotected intercourse. "We hypothesize that the decreased expression of BDNF is related to the pathogenesis of some male infertility." (PMID 36661494, 2022).
maple syrup urine disease (1 paper, 2019). An autosomal recessive inherited disorder caused by mutations in the BCKDHA, BCKDHB, DBT, and DLD genes. "Here we analyzed the expression of brain-derived neurotrophic factor (BDNF) and 10 genes required for correct brain functioning in plasma and blood of patients with Urea Cycle Disorders (UCD), Maple Syrup Urine Disease (MSUD) and controls." (PMID 31235756, 2019).
mast cell disease (1 paper, 2017). "In our mouse models, the mast cell disease induced by TRKA/NGF and TRKB/BDNF is strikingly similar to human SM, particularly to WDSM." (PMID 29088753, 2017).
megacolon (1 paper, 2023). "Therefore, the clinical findings of congenital aganglionic megacolon in Pt 7 are likely related to decreased BDNF/TrkB signaling due to ANKRD11 deficiency caused by the deletion of exons 5–9 of the gene." (PMID 36564961, 2023).
megalencephaly (1 paper, 2016). A congenital abnormality in which the occipitofrontal circumference is greater than two standard deviations above the mean for a given age. "At this moment, it is unknown whether this mechanism – zinc dyshomeostasis, MMP activation, BDNF upregulation – operates in sporadic ASD cases, especially ones accompanied by megalencephaly." (PMID 27352957, 2016).
menopausal disorders (1 paper, 2018). "Taken together, these findings indicate that MAI stimulation at SP6 facilitates an estradiol-independent BDNF-NPY cascade, which may contribute to its antidepressant effects in OVX rats, an animal model of menopausal disorders." (PMID 29643431, 2018).
metastasis (1 paper, 2014). The spread or migration of cancer cells from one part of the body (where they first appeared) to another. "Tissue BDNF mRNA was associated with liver and peritoneal metastasis." (PMID 24801982, 2014). "The co-expression of BDNF and TrkB was associated with liver and peritoneal metastasis." (PMID 24801982, 2014). "The BDNF mRNA expression level in CRC tissues was found to be significantly associated with synchronous liver metastasis (P = 0.007) and synchronous peritoneal metastasis (P = 0.026)." (PMID 24801982, 2014).
microphthalmia (1 paper, 2022). Congenital or developmental anomaly in which the eyeballs are abnormally small. "The degree of microphthalmia was paralleled by EtOH dose-dependent reductions in eye and brain BDNF levels (ELISA) and PMP22 expression (FACS), and by dramatic increases in brain (FACS), and eye caspase-3 activity (FACS)." (PMID 36613580, 2022).
Miscarriage (1 paper, 2023). A pregnancy that ends at a stage in which the fetus is incapable of surviving on its own, defined as the spontaneous loss of a fetus before the 22th week of pregnancy. "Additionally, patients who experienced a miscarriage had a higher secretion of BDNF than in the fertile pregnant controls (p = 0.0048, median 0.94 before ET vs. 0.00 pg/ml; p = 0.0019, median 8.93 vs. 0.00 pg/ml)." (PMID 37744353, 2023).
myasthenia gravis (1 paper, 2022). Myasthenia gravis (MG) is a rare, clinically heterogeneous, autoimmune disorder of the neuromuscular junction characterized by fatigable weakness of voluntary muscles. "Additionally, serum brain-derived neurotrophic factor levels were significantly higher in myasthenia gravis patients (P = 0.001, d = 2.040)." (PMID 35198977, 2022).
myositis (1 paper, 2024). "This study aims to test if brain-derived neurotrophic factor (BDNF) deficiency per se is sufficient to cause myositis and determine its underlying mechanism." (PMID 39531828, 2024). "Studies to determine the BDNF content in the skeletal muscle of myositis patients is warranted to further confirm the causative role of BDNF in myositis onset." (PMID 39531828, 2024). "Together, our study demonstrates that insufficient BDNF production in mouse muscle causes the development of pathological features of myositis via enhancing oxidative stress, necroptosis, and pyroptosis in myofibers." (PMID 39531828, 2024). "Together, our results strongly suggest that BDNF deficiency in skeletal muscle is an unrecognized cause of necroptotic and pyroptotic cell damage, leading to the development of myositis." (PMID 39531828, 2024). "Therefore, this study aims to test if BDNF deficiency per se is sufficient to cause myositis-like muscle damage and determine its underlying mechanism." (PMID 39531828, 2024). "Given that mitochondrial dysfunction has been observed in the skeletal muscles of myositis patients, and that BDNF is a novel regulator of mitochondria clearance, insufficient BDNF production in skeletal muscle might cause muscle damage and weakness as observed in myositis patients." (PMID 39531828, 2024). "Hence, further investigation on the potential role of BDNF signaling in NMJ function among myositis patients should be performed in the future, which could provide insights into the neurological consequences of BDNF deficiency in myositis." (PMID 39531828, 2024). "We found that ablating BDNF production in skeletal muscle is sufficient to trigger myositis development in mice." (PMID 39531828, 2024). "In conclusion, our study demonstrates that inadequate BDNF production in mouse muscle contributes to the development of pathological features of myositis via enhancing oxidative stress, necroptosis, and pyroptosis in myofibers." (PMID 39531828, 2024). "Nevertheless, the role of BDNF in myositis pathogenesis has not been examined and it remains unknown if BDNF content is reduced in the muscle of myositis patients." (PMID 39531828, 2024).
neonatal abstinence syndrome (1 paper, 2017). A constellation of neurobehavioral features observed in a neonate following antenatal exposure to drugs including opioids, benzodiazepines, and selective serotonin reuptake inhibitors. "Brain-derived neurotrophic factor levels among infants with neonatal abstinence syndrome and comparisons across levels in the given variables." (PMID 29164087, 2017).
Nervous (1 paper, 2010). "Interestingly, altered BDNF AF levels were found associated with Central Nervous System (CNS) abnormalities of the fetus, suggesting that AF BDNF levels could be indicative of fetal CNS development." (PMID 20141627, 2010).
neural tumors (1 paper, 2024). "High-neural tumors also exhibit increased functional connectivity in magnetencephalography and resting-state magnet resonance imaging and can be detected via DNA analytes and brain-derived neurotrophic factor in patients’ plasma." (PMID 38760585, 2024).
neuralgia (1 paper, 2022). "However, for patients with post-herpetic neuralgia, lower levels of BDNF in CSF have been reported." (PMID 35061744, 2022).
non-Hodgkin lymphoma (1 paper, 2022). Distinct from Hodgkin lymphoma both morphologically and biologically, non-Hodgkin lymphoma (NHL) is characterized by the absence of Reed-Sternberg cells, can occur at any age, and usually presents as a localized or generalized lymphadenopathy associated with fever and weight loss. "Correlation between BDNF levels and CIPN by TNS-r was also reported in 22 non-Hodgkin lymphoma patients treated with vincristine." (PMID 35360655, 2022).
Nystagmus (1 paper, 2016). Rhythmic, involuntary oscillations of one or both eyes related to abnormality in fixation, conjugate gaze, or vestibular mechanisms. "The changes induced by BDNF treatment might have potential therapeutic value in dampening/reducing uncontrolled eye oscillations in nystagmus." (PMID 27802489, 2016). "Further studies are needed, but the data suggest that treatment of the extraocular muscles with BDNF might be able to modify and dampen the uncontrolled movements in nystagmus." (PMID 27802489, 2016). "Our previous study showing reduced/absent BDNF expression in EOM of children with nystagmus suggests that providing BDNF to the EOM may have the ability to dampen the uncontrolled oscillatory movements." (PMID 27802489, 2016).